SOX11 (SRY-box transcription factor 11)
Diseases named in the same sentence as SOX11 in open-access papers (continued):
Sharing a sentence is not in itself a finding about the gene and the disease.
tumor (continued). "We identified potential downstream effectors of SOX11 during both microinvasive and invasive tumour growth stages, including several with established links to regulation of progenitor cell function and prenatal developmental growth." (PMID 28707729, 2017). "Expression profiling of the lesions and tumours that formed after intraductal injection of DCIS.com cells expressing SOX11 identified a large number of candidate downstream effectors, during both the microinvasive and invasive growth stages." (PMID 28707729, 2017). "Quantitative polymerase chain reaction (qPCR) analysis revealed higher levels of SOX11, FHAD1, HORMAD1 and TFAP2B expression in DCIS‐SOX11 than in DCIS‐LacZ tumours." (PMID 28707729, 2017). "The role of SOX11 in other cancers has been particularly dependent on cancer type, with reports suggesting both oncogenic and tumor suppressor roles." (PMID 26894864, 2016). "S100P, CXCL11, and SRY (Sex Determining Region Y)-Box 11 (SOX11) display higher expression in tumor samples." (PMID 27857161, 2016). "SOX11 protein expression has been shown to correlate to increased and decreased survival in different tumor entities, emphasizing different function depending on molecular and cellular context." (PMID 25880212, 2015). "A previous study has shown that another member of the SOX family, SOX11, can also act as a tumor suppressor in NPC cells." (PMID 25427424, 2014). "Accordingly, tumor burden was significantly reduced in mice injected with the NGN2/SOX11-expressing virus when examined at 35 days posttransplantation." (PMID 25321470, 2014). "In combination, the simplicity of the flow cytometry protocol and the disease-defining property of the SOX11 antigen suggest its future use in both routine diagnostics and for detection of circulating tumor cells during patient follow-up." (PMID 22738398, 2012). "Together these data suggest a key growth regulatory role of SOX11 in these neoplasms and emphasize the need for functional antibodies for experimental use in various technologies, including imaging and flow cytometry applications." (PMID 22738398, 2012). "Of note, identification of tumor cells in flow cytometry normally requires the use of multiple markers and advanced gating strategies, emphasizes the strength of SOX11 as a discriminate antigen." (PMID 22738398, 2012). "IHC-P staining confirmed specific detection of SOX11 in CD20-expressing human tumor cells on a murine background." (PMID 22738398, 2012). "The possibility to re-express SOX11 indicates a potential use of epigenetic drugs to affect cell growth through common cell regulatory pathways, controlled by SOX11, and other tumour suppressors that are silenced in EOC." (PMID 21943380, 2011). "It is of major interest that SOX11 can be used to further subdivide high grade tumours, which also indicates a functional role for SOX11 as a tumour suppressor." (PMID 21943380, 2011). "In the present study, we used functional and epigenetic analyses of B cell malignancies to demonstrate a regulatory mechanism of SOX11 expression on tumor cell growth." (PMID 20624318, 2010). "Notably, SOX11 is overexpressed in a wide spectrum of human malignancies, including mantle cell lymphoma, glioma, breast and ovarian carcinomas, gastrointestinal cancers, HNSCC, leukemia, Burkitt’s lymphoma, and pediatric medulloblastoma and ependymoma." (PMID 41511366, 2026). "The downregulation of FOXC1, FOXC2, and SOX11 suggests these transcription factors may play a role in maintaining tumour differentiation and regulating metastatic behaviour, warranting further investigation." (PMID 40683913, 2025). "Importantly, Sox11-dependent expression of a selection of genes from bulk RNA-seq clusters 1, 2, and 8, and of the tumor suppressor Gata5, a paralog of Gata4, had already been proven by targeted by qRT-PCR analyses, or was newly confirmed." (PMID 40393982, 2025).
tumor (continued). "Moreover, SOX11 and SOX18 are closely associated with tumor TMB and NEO, which is of significant importance in predicting immune efficacy and patient prognosis, providing new treatment strategies for personalized immunotherapy." (PMID 38331879, 2024). "MiR-145–5p suppress neuroendocrine differentiation and tumor progression via SOX11/MYCN axis." (PMID 38887275, 2024). "Moreover, Sox11 was shown as a potential oncogenic regulator of tumour development through its ability to promote cellular migration." (PMID 39039706, 2024). "Given the close relationship between PI3K/Akt signalling and tumour cell migratory, proliferative, and autophagic activity, studies of the ability of Sox11 to modulate the PI3K/AKT pathway may offer insight into the best approaches to managing OSCC." (PMID 39039706, 2024). "The results of this study further demonstrated a central role for the PI3K/AKT pathway in the regulation of Sox11 expression as a mechanism facilitating the maintenance of tumour cell survival and proliferation, providing a foundation to guide future OSCC treatment." (PMID 39039706, 2024). "As such, Sox11 may play a tissue‐ and context‐specific role in the progression of different tumours." (PMID 39039706, 2024). "These cases are often blastic or pleomorphic with high tumour cell proliferation, high genomic complexity, may express TdT, and may lack SOX11." (PMID 36454275, 2023). "SOX11 is maintained at low levels as a tumor suppressor in HCC." (PMID 38084140, 2023). "However, caution must be taken in the event of negative staining results: of 70 GBMS, one case was stained only with CD34, and two tumours stained only with SOX11." (PMID 37568909, 2023). "Our findings suggest that miR-145-5p can inhibit NED and tumor growth by targeting SOX11, which regulates the expression of MYCN, and that this could be a novel therapeutic strategy for preventing the progression of PCa." (PMID 35368699, 2022). "The correlation between SOX11 expression and immune cell content might depend on tumor cell type according to the ESTIMATE algorithm." (PMID 36551589, 2022). "SOX11 was reported to act as both an oncogenic and a tumor suppressor." (PMID 36551589, 2022). "We compared the differences in SOX11 expression levels at different tumor stages." (PMID 36551589, 2022). "Mechanistically, we found that SOX11 is a direct target of miR-145-5p, which might mediate miR-145-5p’s tumor-suppressive functions by regulating MYCN during NED of PCa cells." (PMID 35368699, 2022). "In addition, aberrant SOX11 expression was associated with stem cell scoring, EMT-related genes, MSI, TMB and the tumor immune microenvironment in different cancer types." (PMID 36551589, 2022). "Interestingly, SOX11 was recently reported to act as a tumor suppressor in PCa, since its overexpression suppressed the migration and invasion of PCa cells." (PMID 36246971, 2022). "MiR-211 acts as a tumor suppressor or tumor promoter in malignancies by targeting SOX11." (PMID 35912006, 2022). "The impaired tumor progression seen in the Granta-519 MCL tumors following DPN treatment may therefore involve a DPN-mediated suppression of SOX11 expression." (PMID 35804870, 2022). "However, liver metastases were detected more frequently in mice that had primary tumours with reduced Sox11 levels." (PMID 33969421, 2021). "SOX4 and SOX11, markers of neurogenic RPCs, were also expressed in most tumor cone clusters." (PMID 34003213, 2021). "A previous study also indicates that SOX11 plays tumor-suppressive roles in cancer development." (PMID 33536579, 2021). "To explore whether sustained reactivation of SOX11 promotes tumour progression, we injected luciferase-tagged iEV and iSOX11 cells into the mammary fat pad." (PMID 32909943, 2020).
tumor (continued). "To test the functional roles of ASCL1 and SOX11 in DIPG tumor cells, we used CRISPR/Cas9-mediated gene editing to inactivate them individually and in combination in ACVR1 mutant (SU-DIPG-IV, SU-DIPG-XXI, SU-DIPG-XXXVI, HSJD-DIPG-007) or wild-type (SU-DIPG-VI) cells." (PMID 32142668, 2020). "Moreover, a database analysis using the Cancer Genome Atlas suggested that SOX11 mRNA expression was high during the tumor development process." (PMID 32586027, 2020). "Notably, we did not observe the direct association of TET3 with these factors, and found that several tumor suppressor genes (CDKN2B, ZIC2, and miR-196a) and oncogenes (PAX2, IL2RA, SOX11, and PAK7) were associated with TET3 in AML biology." (PMID 32209730, 2020). "Induction of SOX11 expression led to larger tumour burden in the brain and reduced survival." (PMID 32909943, 2020). "This cluster also enriched some well‐known stemness markers such as Sox11, Sox4, Nestin, Ptprs, and Cdk4, suggesting that they may function as the TICs in the tumor." (PMID 33173731, 2020). "To explore whether sustained reactivation of SOX11 promotes tumour progression, we assessed features of iSOX11 spheroids." (PMID 32909943, 2020). "These existing studies imply that the role of SOX11 in tumor development and progression may be tissue specific and cell context dependent." (PMID 30922366, 2019). "It again suggests that the function of SOX11 in tumor progression may be tissue specific and cell context dependent." (PMID 30922366, 2019). "High expression of SOX11 in tumor cells could lead to a more aggressive disease course with increased proliferation and cell survival, by activating FAK and CXCR4." (PMID 29520657, 2018). "SOX11 is coexpressed among a cluster of genes that identify a distinct DCIS subgroup with gene expression characteristics that are more similar to those of advanced tumours." (PMID 28707729, 2017). "This overexpression is correlated with smaller tumor size and milder tumor grade, indicating that SOX11 could inhibit growth and progression of BC, and promote absence of lymph node metastasis." (PMID 27857161, 2016). "Importantly, direct injection of NGN2/SOX11-expressing lentivirus into a preexisting tumor mass also resulted in the appearance of neuron-like cells." (PMID 25321470, 2014). "Furthermore, SOX11 expression correlates to promoter methylation and regulates tumor growth in hematopoietic malignancies." (PMID 23658834, 2013). "So, he suggested that SOX11 plays a functional role in regulation of tumor growth." (PMID 24188789, 2013). "Furthermore, SOX11 was found to promote HNSCC tumor growth and the expression of TWIST1 in vivo." (PMID 41511366, 2026). "In addition to its pivotal functions in embryonic development and organogenesis, Sox11 emerged as a context-dependent tumor-promoting as well as tumor-suppressing factor with the capacity to both positively and negatively regulate cancer cell proliferation, migration, and invasion." (PMID 40393982, 2025). "Additionally, IHC for SOX11 was done on the tumor in the appendix." (PMID 39328717, 2024). "High TPS was associated with genes such as SOX11 and GSX1, which may promote tumour proliferation, whereas Low TPS was enriched with immune-related genes like LILRB4, highlighting the complex interactions within the tumour microenvironment." (PMID 39457550, 2024). "To confirm whether or not Sox11 is associated with metabolism type in the tumour cells, we checked ECAR and OCR in tumour cells." (PMID 39039706, 2024).
tumor (continued). "Interestingly, IDH-mutant tumours were strongly associated with proneural/neural/OPC gene expression signatures; this may explain the more common immunoreactivity of SOX11 in the subset." (PMID 37568909, 2023). "Moreover, SOX11 expression could serve as an indicator of survival outcomes, tumor progression and cellular immune infiltration." (PMID 36551589, 2022). "Currently, the predictive role of SOX11 in the tumor immune microenvironment remains unknown." (PMID 36551589, 2022). "However, SOX11 serves as a tumor suppressor to participate in HCC progression." (PMID 35267473, 2022). "Thus, SOX11 appears to be a pivotal biomarker for predicting tumor grade and survival in BC." (PMID 32043610, 2020). "Similarly, in a group of 127 patients at late tumor invasion stage (T3+T4), 63 cases (49.6%) of the SOX11-positive group showed longer medium survival (43.0 months) than the other 64 cases (50.4%) of the SOX11-negative group (23.0 months) patients (P=0.004, right)." (PMID 24604109, 2014). "As SOX11 is not expressed in normal lymphoid cells, its DNA hypermethylation in some neoplasms without SOX11 expression is most likely functionally inert, and might be associated with reducing epigenetic plasticity in tumor cells." (PMID 21738649, 2011). "Gene regulatory network analysis revealed that top regulators of Group 4 MB tumour cells include EOMES, SOX4, and SOX11." (PMID 41998565, 2026). "Our studies have demonstrated that SOX11 is upregulated by the EGF-EGFR-STAT3 signaling pathway and subsequently activates EMT-TFs, facilitating EMT and tumor progression." (PMID 41511366, 2026). "The expression of SOX12 was higher in the tumor cell subgroup compared to normal subgroup, whereas other SOX transcripts, including SOX2, SOX5, SOX9, SOX11, and SOX15, had low expression in tumor clusters." (PMID 40593465, 2025). "Eight genes were differentially expressed at both the mRNA and protein levels, with ASCL1, EDNRB, INSM1, SOX11, SOX4, SOX8, and SIX1 showing reduced expression in tumor tissues, and CTNNB1 showing increased expression compared with para-cancer tissues." (PMID 40771813, 2025). "Sox11 emerged as a key driver of TKA-organoid pEMT with additional, TGF-β1-independent gene regulatory activities related to normal gut functions and tumor suppression." (PMID 40393982, 2025). "Based on the findings above, we infer that SOX11 and SOX18 have an intimate connection with tumor immunity." (PMID 38331879, 2024). "SOX11 knockout (SOX11KO) significantly reduced PRDX2 expression, and SOX11KO and PRDX2 knockdown (PRDX2KD) had increased ROS levels and ROS-mediated tumor cell death upon treatment with drugs, compared to control MCL cell lines." (PMID 38570586, 2024). "GSX1 and SOX11 have been identified as critical marker genes for the High TPS group, indicating their significant influence on tumour dynamics." (PMID 39457550, 2024). "Because USP9X affects cell migration and angiogenesis by elevating CCND1-mediated SOX11 expression, USP9X suppression leads to the downregulation of USP9X protein levels in Z-138 and Jeko-1 cell lines and inhibits tumor development in mice in vivo." (PMID 39664521, 2024). "Since little is known of the function of SOX genes in NB, we evaluated the expression of SOX11 and SOX4 in a cohort of 395 normal and tumor tissues sequenced in the TARGET dataset." (PMID 38653778, 2024). "Additionally, we used TCGA pan-cancer data to analyze the correlations among SOX11 expression and survival outcomes, clinical features, stemness, microsatellite instability (MSI), tumor mutation burden (TMB), mismatch repair (MMR) related genes and the tumor immune microenvironment." (PMID 36551589, 2022).
tumor (continued). "In MCL, the role of SOX11 in tumor growth and development has initially been mainly related to the terminal B-cell differentiation blockade, PAX5 being one of key targets of SOX11, whose silencing induces BLIMP1 expression and plasmacytic differentiation." (PMID 35804999, 2022). "Then, the potential relationships between SOX11 expression and clinicopathological phenotypes, stemness score, TMB, MSI, MMR-related genes and tumor immune microenvironment were further explored." (PMID 36551589, 2022). "The diagnosis of MCL was confirmed by the expression of CD20, CD5, cyclin D1, SOX11, and SAMHD1 of tumor cells." (PMID 34976810, 2021). "A reduced number of tumour cells that express Keratin 14 and SMA were detected in tumours with reduced Sox11 levels compared to controls." (PMID 33969421, 2021). "In the present study, we selected tumor suppressor lncRNA MEG3 and its related molecules (miR-9-5p and SOX11) to explore the effects of those interactions on HCC." (PMID 31531526, 2019). "There was only one tumor suppressor (CSF2) and one cancer census gene in Cluster 3 (USP6); there are four tumor suppressors (GALR1, IRF4, PTPRT and SOX11) and one more cancer census gene in Cluster 4 (NRG1)." (PMID 28198667, 2017). "To validate our findings regarding CNVs identified by CNVpanelizer, we investigated SOX11, CDX2, MMP9, CARD11 and EDEM2 copy numbers in 41 tumour sections by gene-specific FISH." (PMID 28120820, 2017). "Control and SOX11-overexpressing SGC-7901 cells were injected orthotopically into nude mice and tumor growth was examined." (PMID 24604109, 2014). "The expression of these proteins correlated with tumor areas in which cells had more “active” appearing nuclear features, and high expression of ADAM12, FAP, and WISP1, and low expression of SOX11, correlated with worse clinical outcome." (PMID 24402778, 2014). "A tumor specific nuclear algorithm (IHC-MARK) was developed and used to evaluate the nuclear SOX11 protein expression." (PMID 21943380, 2011). "Our work provides initial evidence for human-enriched UBC states and suggests that SOX4 and SOX11 may drive neurogenesis in UBC and gene expression in a subset of Group 4 MB tumour cells." (PMID 41998565, 2026). "The IHC analysis of xenograft tumor tissues showed that the overall staining intensity of PCNA, Ki67, and TWIST1 was markedly increased in the SOX11 overexpression group but decreased in the SOX11 knockdown group when compared with the control group." (PMID 41511366, 2026). "In sum, the bulk RNA-seq analyses suggested that Sox11 might play a hitherto unknown role in intestinal tissue homeostasis and undergoes a TGF-β1-induced switch from potential tumor suppressor to tumor-promoting factor." (PMID 40393982, 2025). "Although SOX11 expression in unstratified tumor samples was not significantly higher than in normal tissue, SOX11 expression steadily increased during tumor progression." (PMID 40393982, 2025). "Immunohistochemical (IHC) staining revealed that the tumor cells were diffusely positive for SOX11 but negative for SATB2, CD56, S100, and TLE1." (PMID 40791569, 2025). "Besides, the data indicated that higher levels of Sox11 expression were found to be significantly related to the TNM stage (p = 0.0033), degree of tumour differentiation (p = 0.0176), and tumour size (p = 0.0005) in OSCC patients." (PMID 39039706, 2024). "Besides, the knocking down of Sox11 in OSCC cells suppresses the PI3K/AKT pathway and subsequently suppresses the proliferation and migration of tumour cells." (PMID 39039706, 2024). "At the molecular level, the juxtaposition of HNRNPH1 and SOX11 super-enhancers to MYC cis-regulatory elements, through a mechanism of distance looping, appears to be responsible for MYC overexpression and the abnormal proliferation of group 3 tumor cells." (PMID 37568705, 2023).